PLXNA1 (plexin A1)
Description:
Coreceptor for SEMA3A, SEMA3C, SEMA3F and SEMA6D. Necessary for signaling by class 3 semaphorins and subsequent remodeling of the cytoskeleton. Plays a role in axon guidance, invasive growth and cell migration. Class 3 semaphorins bind to a complex composed of a neuropilin and a plexin. The plexin modulates the affinity of the complex for specific semaphorins, and its cytoplasmic domain is required for the activation of down-stream signaling events in the cytoplasm. Acts as coreceptor of TREM2 for SEMA6D in dendritic cells and is involved in the generation of immune responses and skeletal homeostasis.
Synonyms: NOV; PLXN1; DWOPNED; NOVP; PLEXIN-A1
Tractability: Antibody: its Gene Ontology location is reachable by antibodies, with high confidence; UniProt places it where antibodies can reach, with medium confidence; UniProt predicts a signal peptide or a membrane-spanning region. PROTAC: ubiquitination databases record sites on it; its protein half-life has been measured.
Gene: Protein-coding gene on chromosome 3 (126,982,693 to 127,037,389, forward strand). Ensembl gene ENSG00000114554.
Subcellular location: Cell membrane
Subcellular location (Human Protein Atlas): Cytosol; Nucleoplasm; Basal body; Centrosome
Pathways (Reactome):
Developmental Biology: CRMPs in Sema3A signaling; Other semaphorin interactions; SEMA3A-Plexin repulsion signaling by inhibiting Integrin adhesion; Sema3A PAK dependent Axon repulsion
Signal Transduction: RHOD GTPase cycle; RND1 GTPase cycle
Gene Ontology:
Molecular function: semaphorin receptor activity
Biological process: semaphorin-plexin signaling pathway; T cell activation via T cell receptor contact with antigen bound to MHC molecule on antigen presenting cell; neuron projection guidance; regulation of cell migration; synapse assembly; gonadotrophin-releasing hormone neuronal migration to the hypothalamus; olfactory nerve formation
Cellular component: extracellular exosome; plasma membrane; semaphorin receptor complex; glutamatergic synapse; membrane; synapse
Genetic constraint (gnomAD): Loss-of-function variants: 76 observed, 189.29 expected, observed/expected ratio (o/e) 0.4, 90% interval 0.33 to 0.49. The upper end of that interval is the gene's LOEUF score, 0.49, which puts it in group 2 of 6, group 1 being the genes least tolerant of losing a copy. Missense variants: 2,106 observed, 2,699.2 expected, observed/expected ratio (o/e) 0.78, 90% interval 0.75 to 0.81. Synonymous variants: 1,132 observed, 1,165.6 expected, observed/expected ratio (o/e) 0.97, 90% interval 0.92 to 1.02.
Homologues: Orthologues: chimpanzee PLXNA1 (99% identical), macaque PLXNA1 (99% identical), dog PLXNA1 (97% identical), guinea pig PLXNA1 (97% identical), rat Plxna1 (96% identical), mouse Plxna1 (96% identical), pig PLXNA1 (95% identical), rabbit PLXNA1 (90% identical), tropical clawed frog plxna1 (84% identical), zebrafish plxna1a (81% identical), zebrafish plxna1b (72% identical). Paralogues in human: PLXNA3 (66% identical), PLXNA4 (64% identical), PLXNA2 (64% identical), PLXNB1 (36% identical), PLXNB3 (34% identical), PLXND1 (33% identical), PLXNB2 (32% identical), PLXNC1 (21% identical).
Diseases named in the same sentence as PLXNA1 in open-access papers:
PLXNA1 is named in the same sentence as 53 diseases in open-access papers, as found by Europe PMC text mining. Sharing a sentence is not in itself a finding about the gene and the disease. The quoted sentences say what the papers report.
breast carcinoma (9 papers, 2005 to 2024). "Thus, as an alternative hypothesis, VEGFR3 and PLXNA1 expression on PBMCs could play a role as a biomarker to determine breast cancer cases susceptible to immunotherapy." (PMID 28607365, 2017). "Similar results were obtained for the two latter genes in the enrichment analysis using Metascape, which also highlighted the involvement of CPNE1 and PLXNA1 in breast cancer." (PMID 38184718, 2024). "NP1 complexing with plexin-A1 involving both VEGF and SEMA3a has been implicated in the chemotaxis of breast cancer cell lines." (PMID 25889301, 2015). "It has recently been reported that MDA-MB-231 breast carcinoma cells express sema-3A and plexin-A1, which can both bind to NP-1." (PMID 15655556, 2005). "Neuropilin-1 has also been implicated in chemotaxis of breast cancer cell lines through autocrine pathways involving both VEGF and SEMA3a by complexing with plexin-A1." (PMID 15956974, 2005). "In this analysis, expression of 2 genes (CENPF, PLXNA1) showed significant differences between groups that died from breast cancer (n = 388) vs alive/lost to follow up (n = 962) (p < 0.05), and significantly predicted differences in length of survival in Kaplan–Meier analyses (p < 0.05)." (PMID 32734521, 2020). "Lastly, we found that NRP1, NRP2, PLXNA1, C1, and D1 had the highest correlation with the expression of immune checkpoint molecules PD1/PDL1 and CTLA-4 in breast cancer." (PMID 32640719, 2020). "Interestingly, ROC analysis determined that the combined expression of VEGFR3 and PLXNA1 on PBMCs could differentiate TNBC cases from other breast cancer subtypes with a high sensitivity and specificity, providing evidence for a TNBC subtype-specific expression in PBMCs." (PMID 28607365, 2017). "Contrary to observations in the plasma, a majority of the studied PBMC genes PlGF, VEGF, TGFβ1, PLXNA1 and VEGFR3, indicated similar expression in both early onset and older breast cancer patients, with controls showing higher variability between the two age groups." (PMID 28607365, 2017). "Our analysis showed that PLXNA3, B2, and C1 were significantly upregulated, and NRP1, NRP2, PLXNA1, A2, A4 were significantly downregulated, while the rest of the members (PLXNB1, B3 and D1) were not differentially expressed in breast cancer tumors." (PMID 32640719, 2020).
glioblastoma (7 papers, 2016 to 2025). The most malignant astrocytic tumor (WHO grade IV). "Thus, screening Plexin-A1 expression and targeting Plexin-A1 in glioblastoma patients exhibit diagnostic and therapeutic value." (PMID 27506939, 2016). "We previously showed that the disruption of the NRP1/Plexin-A1 dimer suppresses vascular endothelial growth factor type A (VEGFA)-induced migration of glioblastoma U-118MG cells." (PMID 31652529, 2019). "Q-RTPCR and tissue-array analyses showed here that Plexin-A1 is highly expressed in glioblastoma and that the highest level of expression correlates with the worse survival of patients." (PMID 27506939, 2016). "Finally, we examined TCGA survival data in both low grade glioma and glioblastoma based off expression levels of these three transcripts: Sema3A, Nrp1, PlxnA1." (PMID 33302912, 2020). "However, studies of PLXNA1 –SEMA3 signaling in glioblastoma and pancreas cancer have pointed to an opposite role of promotion of migration, invasion, and growth presumably through different regulation and function of effector downstream signaling." (PMID 26962861, 2016). "Based on this study, the SEMA3F-mimetic bsAb P1943-Nb2cL shows promise for preclinical mouse models and eventually clinical trials targeting glioblastoma and other cancers that express high levels of NRP2 and PLXNA1." (PMID 41391772, 2025).
gastric cancer (5 papers, 2017 to 2024). A primary or metastatic malignant neoplasm involving the stomach. "Furthermore, a 2016 study using samples of human gastric cancer tissues has also shown an increased prevalence of Sema6D and Plexin A1 in endothelial vascular cells and an association of Sema6D and plexin-A1 with VEGFR2." (PMID 38375479, 2024). "Using immunohistochemical and fluorescent staining, we found that plexin-A1 was highly expressed within gastric cancer, in both the tumor cells and the vascular endothelial cells within the tumor, but not in the adjacent normal gastric tissues." (PMID 29262812, 2017). "Plexin-A1 and VEGFR2 are co-localized in human gastric cancer cells and tumor-associated vascular endothelial cells." (PMID 29262812, 2017). "Angiogenesis requires epithelial cells efficient migration and tube formation, thus we used transwell assay and tube formation methods to evaluate the influence of gastric cancer cells secretion on HUVEC by interfering plexin-A1 expression." (PMID 29262812, 2017). "This complex signals have been reported, we therefore further addressed the relationship between VEGFR2 and plexin-A1 in gastric cancer cells." (PMID 29262812, 2017). "We found that isoprenaline stimulated vascular endothelial growth factor (VEGF) secretion in gastric cancer cells and plexin-A1 expression was induced by human recombinant VEGF165 in both gastric cancer cells and vascular endothelial cells." (PMID 29262812, 2017). "Meanwhile, we found that human recombinant VEGF165 treatment up-regulate expression of plexin-A1 in both HUVECs and gastric cancer cells." (PMID 29262812, 2017). "However, plexin-A1 was positively correlated with angiogenesis by detecting microvessel density (MVD) in gastric cancer." (PMID 29262812, 2017). "Furthermore, interfere with plexin-A1 expression in gastric cancer cells influence HUVEC tube formation, migration and tumor growth in vivo." (PMID 29262812, 2017). "The expression of plexin-A1 in gastric cancer cells can further influence tumor angiogenesis." (PMID 29262812, 2017). "Isoprenaline up-regulated expression of plexin-A1 and VEGFR2 in gastric cancer cells, and induction of VEGFR2 was dependent on expression of plexin-A1 as knockdown of plexin-A1 expression inhibited isoprenaline-induced up-regulation of VEGFR2." (PMID 29262812, 2017). "We performed real-time PCR analysis in 2 gastric cancer cell lines (HGC27 and MGC803) to determine plexin-A1 expression at transcription levels after isoprenaline treatment for 3 h." (PMID 29262812, 2017). "The present study reveals a direct link between stress-related hormones and angiogenesis in gastric cancer, which up-regulate plexin-A1 and VEGFR2 expression in gastric cancer cells to promote tumor angiogenesis via VEGF secretion." (PMID 29262812, 2017). "Collectively, these findings indicate that isoprenaline up-regulates plexin-A1 and VEGFR2 expression via β2-AR in gastric cancer cells." (PMID 29262812, 2017). "Plexin-A1 was highly expressed within gastric cancer cell in siNC group, but no expression in siplexin-A1 group." (PMID 29262812, 2017). "Given that plexin-A1/VEGFR2 play a critical role in cardiac morphogenesis and angiogenesis, we further investigated the expression and functional relationship between plexin-A1 and VEGFR2 in gastric tumors and gastric cancer cell lines." (PMID 29262812, 2017). "This study reveals a novel molecular mechanism that a stress signal like isoprenaline may enhance angiogenesis via activating plexin-A1/VEGFR2 signaling pathway in gastric cancer, which may be a potential target in development of an anti-angiogenic therapy for gastric cancer." (PMID 29262812, 2017). "We found that plexin-A1 and VEGFR2 proteins were highly expressed in gastric cancer cells but not in normal gastric tissues." (PMID 29262812, 2017).
glioma (5 papers, 2020 to 2025). A benign or malignant brain and spinal cord tumor that arises from glial cells (astrocytes, oligodendrocytes, ependymal cells). "While previous studies have shown that Nrp1 is expressed in high and low grade glioma biopsies, our study is the first to show that higher expression of Nrp1, PlxnA1 and Sema3A are all associated with decreased survival in both GBM and LGG cohorts." (PMID 33302912, 2020). "This is consistent with previous reports that SEMA3F forms a complex with NRP2 and PLXNA1 within 5 min upon treatment on human glioma cells and induced the reduction in phosphorylation of downstream signaling molecules between 5 and 20 min." (PMID 41391772, 2025). "Although the median survival for Low grade glioma patients with low expression of Sema3A/Nrp1/PlxnA1 is significantly greater than those with high expression, the curves do converge at long-term endpoints." (PMID 33302912, 2020). "Plexin-A1 TMD-mimicking peptides disrupt complex formation between neuropilin-1 and Plexin-A1, a complex that forms in gliomas with poor prognoses, and the Plexin-A1 TMD peptides slow both tumor growth and metastasis in cell culture models." (PMID 32604992, 2020). "The mechanism of EGCG+HC may be through the downregulation of SEMA3A and SEMA3F transcript expression which may play some roles in inhibiting the glioma proliferation and halts invasion via Plexin A1 (PLXNA1) and B2 (PLXNB2) receptors." (PMID 35392560, 2022).
pancreatic cancer (3 papers, 2015 to 2022). "We selected the PLXNA1 c.2587G>A variant for further study for a number of reasons: Gene expression studies have recently implied plexin A receptor–SEMA3A signaling in pancreas cancer progression." (PMID 26962861, 2016). "Pancreatic cancer cells expressing mutant PLXNA1 showed activation of Rho-GTPase CDC42, cofilin, and MAPK signaling which was accompanied by cytoskeletal and expansion disorganization." (PMID 26962861, 2016). "It is intriguing that gene expression findings obtained from 293T cells transfected with wild type or mutant PLXNA1 align, in part, with previous findings of activated downstream signaling of plexin A1 receptors in pancreas cancer cells." (PMID 26962861, 2016). "Plexin A1 activation via SEMA3 treatment in different pancreas cancer cell lines has been previously shown to activate Rac1, GSK3β and p44/p42 MAPK signaling." (PMID 26962861, 2016). "In one recent example, in a genomic characterization of pancreatic ductal adenocarcinoma (the major type of pancreatic cancer) high expression of Sema3A and PlxnA1 was found to co-segregate with poor patient survival." (PMID 25624520, 2015). "This included elements of the Hedgehog signaling pathway (SHH, GAS1), semaphorin signaling (SEMA3A, PLXNA1, PLXNB2, PLXND1, PLXNA2, FARP1, FARP2) and also axon guidance pathways (ROBO1, SLIT1, SLIT3 and SLITRK2), all notable for their involvement in pancreatic cancer progression and metastasis." (PMID 36429078, 2022).
brain tumor (2 papers, 2020 to 2025). "While SEMA3F suppresses U87 migration via the NRP2/PLXNA1 receptor complex, SEMA3A suppresses brain tumor stem cell proliferation but enhances migration through NRP1/PLXNA1 complex, and PLXNA1-knockdown reduced the growth of GBM in an mice model." (PMID 40533501, 2025). "We hypothesized that Sema3A directly inhibits brain tumor stem cell (BTSC) proliferation and drives invasion via Neuropilin 1 (Nrp1) and Plexin A1 (PlxnA1) receptors." (PMID 33302912, 2020).
developmental delay (2 papers, 2021 to 2024). "We propose that different biallelic and monoallelic variants in PLXNA1 result in a novel neurodevelopmental syndrome mainly comprising developmental delay, brain, and eye anomalies." (PMID 34054129, 2021). "In conclusion, our study provides evidence that biallelic and monoallelic variants in PLXNA1 result in a novel neurodevelopmental syndrome mainly comprising developmental delay and brain and eye anomalies." (PMID 34054129, 2021).
melanoma (2 papers, 2016 to 2020). A malignant, usually aggressive tumor composed of atypical, neoplastic melanocytes. "In addition, NRP2, PLXNA1, PLXNC1, and PLXNB3 were found to be all positively associated with cell sensitivity to Vemurafenib, which is used for the treatment for late-stage melanoma." (PMID 32640719, 2020). "PLXNA1 and PLXNB2 were in a region of copy loss in 10% of the samples and PLXNA4 was in a region of copy gain in two of the three melanomas that produced metastasis, suggesting that human melanomas harbor alterations of Plexins, in particular PLXNA4 amplification, as previously reported." (PMID 27095580, 2016).
prostate carcinoma (2 papers, 2021 to 2023). A carcinoma that arises from epithelial cells of the prostate gland. "The Perlecan-Semaphorin 3A-Plexin A1-Neuropilin-1 (PSPN) Complex at the cell surface of prostate cancer (PCa) cells influences cell–cell cohesion and dyscohesion." (PMID 33809984, 2021). "In contrast, it was reported that perlecan interacts with a complex of sema3A, plexin-A1, and NRP-1 on the cell surface of prostate cancer cells and that cleavage of this complex by MMP-7 cell-cell bonds promotes the metastatic dissemination of prostate cancer cells." (PMID 37627074, 2023).
Becker muscular dystrophy (1 paper, 2022). Becker muscular dystrophy (BMD) is a neuromuscular disease characterized by progressive muscle wasting and weakness due to degeneration of skeletal, smooth and cardiac muscle. "From the identified disease-specific genes, four genes (ANK3, GALK2, ZBTB45 and PLXNA1) were previously reported to be involved in the pathogenesis of DMD and Becker Muscular Dystrophy (BMD), a milder form of DMD." (PMID 35388741, 2022).
brain inflammation (1 paper, 2014). "Thus, levels of brain inflammation after ICV injection of LPS were significantly reduced in Plexin-A1−/− mice as compared to WT mice." (PMID 24604454, 2014).
cognitive decline (1 paper, 2024). "Further study of WDFY1 and PLXNA1 in different cell types would likely shed light on the context that miR-29a acts to ameliorate cognitive decline with age." (PMID 37989983, 2024).
colon cancer (1 paper, 2020). "In miRNA-targeted genes of READ, ZFPM2 was recommended as a diagnostic biomarker for malignant pleural mesothelioma and PLXNA1 and PTPRU were related to lung cancer or colon cancer." (PMID 32964043, 2020).
Encephalopathy (1 paper, 2014). Encephalopathy is a term that means brain disease, damage, or malfunction. "Results of the present study demonstrated a novel finding regarding the crucial role of Plexin-A1 expressed in mouse microglia, i.e., its activity in enhancing microglial TLR4-mediated signaling in the development of LPS-induced encephalopathy in mice." (PMID 24604454, 2014). "The data suggest that a crosstalk between Plexin-A1 and the TLR4 pathway synergistically enhances the activation of microglia, and thus Plexin-A1-mediated signaling in microglia has an essential role in the development of LPS-induced encephalopathy." (PMID 24604454, 2014).
endometriosis (1 paper, 2015). The growth of functional endometrial tissue in anatomic sites outside the uterine body. "Sema 3A, NRP-1 and Plexin A1 immunostaining were found 100% of peritoneal and deep infiltrating endometriosis samples." (PMID 26720585, 2015). "Higher immunostaining of Sema 3A and Plexin A1 were found in the eutopic endometrial glandular epithelial cells from patients with endometriosis (p = 0.041 and p = 0.025, respectively) than those without endometriosis." (PMID 26720585, 2015). "But the expression of Sema 3A as well as Plexin A1 between the stromal cells from patients with endometriosis and those without endometriosis were not significantly different (p = 0.067 and p = 0.319, respectively)." (PMID 26720585, 2015). "The expression of both NRP-1 and Plexin A1 in glandular epithelial cells of peritoneal endometriosis were also higher than that from eutopic endometrium of women with endometriosis as well as women without endometriosis (all the p values were less than 0.001)." (PMID 26720585, 2015).
esophageal squamous cell carcinoma (1 paper, 2023). Esophageal squamous cell carcinoma (ESCC) is a type of esophageal carcinoma (EC) that can affect any part of the esophagus, but is usually located in the upper or middle third. "Additionally, inhibition of the MAPK signaling pathway through downregulating PLXNA1 has been found to reduce the proliferation, migration, invasion, and metastasis of esophageal squamous cell carcinoma." (PMID 38020758, 2023).
glomerular disease (1 paper, 2015). "It was also shown that an overexpression of Sema3a in podocytes in vivo was associated with glomerular disease, via deregulation of the nephrin/Plexin-A1 interaction thus linking Sema3A and Plexin-A1 to SD complexes." (PMID 26239560, 2015).